RUNX3 (RUNX family transcription factor 3)
Diseases named in the same sentence as RUNX3 in open-access papers (continued):
Sharing a sentence is not in itself a finding about the gene and the disease.
bladder cancer (11 papers, 2007 to 2025). "But clearly, both RUNX3 and PRSS8 were found to be hypermethylated in bladder cancers or bladder cancer cell lines, with RUNX3 hypermethylation directly associated with bladder cancers of smokers." (PMID 23724145, 2013). "Additionally, point mutations of RUNX3 were reported in certain cancers, including human gastric and bladder cancers." (PMID 29254144, 2017). "We had fully expected that both of these marker genes would present a hypermethylation phenotype in the chronically CSE-treated urothelial cells as RUNX3 hypermethylation in bladder cancer is associated with smoking and PRSS8 hypermethylation correlates with bladder cancer progression." (PMID 23724145, 2013). "One possible explanation is that the hypomethylation effect of CSE on RUNX3 in the cultured urothelial cells is the direct effect of CSE; but the hypermethylation of RUNX3 in bladder cancers of smokers is caused by additional indirect mediators, such as inflammatory cytokines." (PMID 23724145, 2013). "Moreover, point mutations of RUNX3 were observed in certain type of human cancers including gastric and bladder cancers." (PMID 23457532, 2013). "Moreover, point mutations of RUNX3 were observed in gastric and bladder cancers." (PMID 24475196, 2014). "Thus, we putatively suggest that nicotinamide treatment may be effective in decreasing the risk of bladder cancer progression by regulation of Myc which is modulated by epigenetic alteration of Runx3, although further experimental validation is needed." (PMID 22028816, 2011). "For example, RUNX3 gene that has been thought as tumor suppressor gene exhibited significant increase at methylation levels in bladder cancer by analyzing 124 tumor tissue samples." (PMID 27594736, 2016). "Earlier, we reported strong evidence suggesting that RUNX3 is a bladder cancer tumor suppressor gene and that it is frequently inactivated by hypermethylation of the promoter region." (PMID 19662195, 2007). "Transformed cells have been shown to have concurrent up-regulation of DNA methyltransferases, so at the stage of fully transformed bladder cancer cells the RUNX3 promoter may after all manifest the hypermethylated phenotype in smokers." (PMID 23724145, 2013). "The RUNX3 tumor suppressor gene promoter was hypomethylated with a significant increase in proportion of the completely unmethylated haplotype after the long-term CSE treatment; whereas RUNX3 promoter hypermethylation was previously reported for bladder cancers of smokers." (PMID 23724145, 2013). "This study shows that RUNX3 gene may be a potential marker for detecting bladder cancer." (PMID 27594736, 2016). "The RUNX3 BS DNA amplicon subjected to sequencing analysis contains 17 CpG sites in the promoter region of this gene, including 2 sites (designated as CpG-1 and CpG-2 in this amplicon) previously shown to be hypermethylated in bladder cancer specimens from smokers." (PMID 23724145, 2013). "Biomarkers with high sensitivity and specificity in multiple panels include RUNX3, SOX1, IRF8, and DAPK; these were used specifically for diagnosis of bladder cancer." (PMID 40141826, 2025). "DNA methylation in tumor suppressor genes such as runt-related transcription factor 3 (RUNX3) occurs significantly earlier in smokers than in nonsmokers with bladder cancer, and such methylation naturally increases with age." (PMID 31013794, 2019). "DNA methylation at the RUNX3 (runt-related transcription factor 3) tumor suppressor gene naturally increases with age and occurs significantly earlier in bladder cancers of smokers than nonsmokers." (PMID 23724145, 2013).
bladder cancer (continued). "The RUNX3 promoter however, showed hypomethylation at CpG-1 in the urothelial cells chronically exposed to CSE, whereas this same site was found to be hypermethylated in bladder cancer specimens of smokers." (PMID 23724145, 2013).
adenoma (10 papers, 2008 to 2024). A neoplasm arising from the epithelium. "We found that the adenoma-prone intestines of Runx3 deficient mice exhibited elevated Myc expression and attributed it to the ability of RUNX3 to attenuate oncogenic Wnt signaling." (PMID 37400551, 2023). "Moreover, Runx3 inactivation in the mouse lung is associated with adenoma formation and reduced latency of oncogenic K-Ras–induced adenocarcinoma formation." (PMID 38240752, 2024). "Subsequently, they investigated whether Runx3 inactivation is causally associated with the development of adenomas." (PMID 25961920, 2016). "Mice with heterozygous deletion of Runx3 induced adenoma in the lung, intestine, and mammary gland within a year, indicating that Runx3 is a gatekeeper for early stages of cancer." (PMID 38240752, 2024). "Earlier studies have indicated involvement of RUNX3 in the suppression of solid tumors—heterozygous knockout (KO) of Runx3 in mouse induces adenomas in lung, mammary gland, and intestine in aged mice." (PMID 38240752, 2024). "At 65 weeks of age, the frequency of adenoma development in the small intestine of Runx3+/− mice was comparable to that of ApcMin/+ mice with the same BALB/c background." (PMID 36766749, 2023). "Targeted inactivation of Runx3 in the mouse lung induces adenomas (ADs), and markedly shortens the latency of ADC formation induced by oncogenic K-Ras." (PMID 36899846, 2023). "Runx3 knockout mouse models showed RUNX3 to be a critical barrier for adenoma to adenocarcinoma progression in the intestine and lung." (PMID 37400551, 2023). "Runx3 inhibits adenoma formation in the lung and its inactivation is an early event in lung adenocarcinoma formation." (PMID 36766749, 2023). "Deletion of mouse lung Runx3 induces adenomas (ADs) and facilitates the development of K-Ras-activated adenocarcinomas (ADCs)." (PMID 37887282, 2023). "RUNX3−/− knockout mice displayed hyperplasia of the stomach on the first day of the birth whereas RUNX3-heterozygous knockout induced adenomas across different tissues after a long latency." (PMID 30535344, 2019). "It would be exciting indeed if Runx3 restoration in K-Ras-activated tumors is able to eliminate not only adenocarcinomas but also adenomas." (PMID 25961920, 2016). "Moreover, Runx3 inactivation was crucial for the progression of adenoma to adenocarcinoma during K-ras-induced lung adenocarcinoma development." (PMID 37400551, 2023). "To date, RUNX3 is the only gene whose inactivation has been shown to be sufficient to induce adenoma, suggesting that abrogation of both the differentiation program and oncogene surveillance mechanism might be required for adenoma development." (PMID 25961920, 2016). "ADAMTS1, CDKN2A, CRABP1, MLH1, NR3C1, RUNX3, and SCGB3A1 showed increasing methylation frequencies from adenomas to carcinomas, while HOXA9, MAL, and MGMT displayed overall equal methylation frequencies in all tumor subgroups." (PMID 19117505, 2008). "However, deregulation of the differentiation program is not sufficient to induce adenoma: so far, Runx3 is the only gene whose inactivation has been reported to induce lung adenoma." (PMID 25961920, 2016). "Moreover, some of them, such as APC and RUNX3 were significantly more frequently methylated in patients with UC and cancer compared to patients with non inflammatory adenocarcinoma and CDH13 was more frequently methylated in patients with UC and dysplasia compared to those with adenoma." (PMID 26862732, 2016).
esophageal cancer (10 papers, 2011 to 2024). A primary or metastatic malignant neoplasm involving the esophagus. "The results of this meta-analysis suggest that RUNX3 methylation is associated with an increased risk, progression as well as worse survival in esophageal cancer." (PMID 25229459, 2014). "In addition, the pooled HR for overall survival (OS) showed that decreased RUNX3 expression was associated with worse survival in esophageal cancer (HR = 4.31, 95% CI = 2.57–7.37, P<0.00001)." (PMID 25229459, 2014). "In addition, RUNX3 methylation is associated with an increased risk and worse survival in esophageal cancer patients." (PMID 25229459, 2014). "In nine studies selected in a meta-analysis examining RUNX3 promoter methylation in the development of esophageal cancer, it was found that RUNX3 methylation of EAC was significantly higher than in healthy controls and patients with BE." (PMID 37175524, 2023). "Previous studies have indicated that RUNX3 is a tumor suppressor gene for several human cancers including esophageal cancer." (PMID 33960364, 2021). "To explain the presence of up-regulated RUNX3 in esophageal cancer of Indian patients, we conjecture two possible explanations." (PMID 32943993, 2020). "Similar studies in esophageal cancer are needed to establish a clearer role of RUNX3 on different characteristics of cancer cells." (PMID 32943993, 2020). "The observation of RUNX3 up-regulation in present study highlights its plausible role in esophageal cancer." (PMID 32943993, 2020). "We therefore, studied the status of EZH2 and its correlation with RUNX3 expression in Indian esophageal cancer patients." (PMID 32943993, 2020). "We conducted a meta-analysis to evaluate the correlation between RUNX3 promoter methylation/low expression and esophageal cancer." (PMID 25229459, 2014). "In this study, we reviewed and performed a meta analysis on the published clinical studies regarding the effect of RUNX3 on patients with esophageal cancer." (PMID 25229459, 2014). "Emerging evidence indicates that RUNX3 is a tumor suppressor gene in several types of human cancers including esophageal cancer." (PMID 25229459, 2014). "However, the association between RUNX3 promoter methylation and esophageal cancer remains unclear." (PMID 25229459, 2014). "The result showed that RUNX3 methylation was significantly higher in esophageal cancer than in normal squamous mucosa from the proximal resection margin or esophageal benign lesions (OR = 2.85, CI = 2.01–4.05, P<0.00001)." (PMID 25229459, 2014). "Here we conducted a systematic review and meta-analysis to quantitatively evaluate the effects of RUNX3 promoter methylation on the incidence of esophageal cancer." (PMID 25229459, 2014). "Further large-scale studies, especially multi-center and well-matched cohort research will provide more insight into the role of RUNX3 in the prognosis and clinical implementation of esophageal cancer patients." (PMID 25229459, 2014). "In a study of a gastric and esophageal cancer cell lines, RUNX3 expression made cancer cells sensitive to TGF-β-induced apoptosis." (PMID 21205319, 2011). "Accordingly, the current study attempts to investigate the hitherto unknown status of RUNX3 in Indian esophageal cancer patients." (PMID 32943993, 2020). "These, along with additional functional biology studies, may provide insights into the biological relevance of RUNX3 in esophageal cancers." (PMID 32943993, 2020). "In conclusion, our meta-analysis showed RUNX3 may play an important role in esophageal cancer initiation and progression." (PMID 25229459, 2014). "Thus, induction of RUNX3 expression by overcoming gene silencing may enhance radiosensitivity against tumor which may have crucial clinical impact for esophageal cancer patients." (PMID 25229459, 2014).
esophageal cancer (continued). "The fact that silencing of RUNX3 gene at the transcriptional level and functional inactivation at the protein level in esophagus cancer are strongly correlated with poor prognosis and may occur in early phase of tumor initiation, making it a promising target for therapeutic approaches." (PMID 25229459, 2014). "Maintaining RUNX3 expression under microenvironment stress conditions, either directly or indirectly or reversing RUNX3 silencing could be a new direction for drug discovery for esophageal cancers." (PMID 25229459, 2014). "The observed positive correlation between RUNX3 and EZH2 (p < 0.03) suggests the possibility of their cooperative and/or interactive role in esophageal cancer, which invites further investigation." (PMID 32943993, 2020). "Consistent with our study, oncomine data analysis also revealed RUNX3 and EZH2 up-regulation in five studies on esophageal cancer, OncomineTM (Compendia Bioscience, Ann Arbor, MI) was used for analysis and visualization." (PMID 32943993, 2020). "The results presented here highlights for the first time the relevance of RUNX3 and EZH2 in esophageal cancer, at least in Indian population." (PMID 32943993, 2020). "Runt-related transcription factor 3 (RUNX3), a tumor suppressor that mediates transforming growth factor TGF-β (Transforming growth factor beta) dependent apoptosis, is reported to be hypermethylated and downregulated in radioresistant esophageal cancer cells." (PMID 29439529, 2018). "Notably, our data suggests that RUNX3 may not be always down-regulated in esophageal cancer, as demonstrated by several studies in different cancers." (PMID 32943993, 2020).
head and neck cancer (10 papers, 2009 to 2022). A primary or metastatic malignant neoplasm affecting the head and neck. "The identification of the tumorigenic mutation R122C of RUNX3 in gastric and head and neck cancers was a significant breakthrough in understanding the mechanism how RUNX3 inhibits carcinogenesis." (PMID 36429115, 2022). "RUNX1 has been reported to be a driver in cancer types and a member of the Runt family, RUNX3, has been found to have an oncogenic role in head and neck cancer." (PMID 33133131, 2020). "Corroborating this view, RUNX3 acts as tumor suppressor in gastro-intestinal cancers and acts as an oncogene in head and neck cancer." (PMID 28456786, 2017). "Upregulation of RUNX3 in head and neck cancer leads to increased cell proliferation and reduced apoptosis." (PMID 27597234, 2016). "Other studies have indicated an oncogenic function for RUNX3 in head and neck cancer." (PMID 28030842, 2017). "In head and neck cancers, the role of RUNX3 is controversial." (PMID 28030842, 2017). "This hypomethylated set of genes included many genes that have previously been shown to be methylated in head and neck cancer, including RASSF1, CHFR, RUNX3, APC, and CDKN2A (p16)." (PMID 23358896, 2013). "Finally, the gene expression levels of RUNX3, TGF-β (a RUNX3-regulating growth factor), and PTHrP (a RUNX3-regulated osteolytic factor) were higher in the tissues of patients with head and neck cancer, including oral cancers, than in normal tissues." (PMID 28030842, 2017).
gastric tumor (9 papers, 2005 to 2024). "To elucidate the RUNX3 methylation by G9a in human biopsy, we compared the expression of RUNX3 and localization of methylated-lysine in human gastric tumor tissues and normal tissues using IF." (PMID 33116296, 2021). "Although levels of RUNX3 were decreased in gastric tumors, the colocalization of methylated-lysine with RUNX3 was increased in human gastric tumor compared to normal tissues." (PMID 33116296, 2021). "Yet another transcriptional factor known to be associated with claudin-1 is Runt-related transcription factor 3 (RUNX3), which is a gastric tumor suppressor." (PMID 31861759, 2019). "Normal gastric mucosa, gastric tumor, and peritumoral tissues were compared for RUNX3 and ARID1A protein expression." (PMID 27566570, 2016). "In addition, RUNX3 protein expression was decreased while G9a expression was increased in human gastric tumor tissue compared to normal human gastric tissue." (PMID 33116296, 2021). "Although we were unable to achieve statistical significance due to the low frequency of RUNX3-expressing tumors, our findings indicate a trend of inverse correlation between RUNX3 and MYC protein levels in gastric tumor." (PMID 37400551, 2023). "We compared RUNX3 and MYC protein levels in human gastric tumor tissue arrays by immunohistochemistry (IHC)." (PMID 37400551, 2023). "A key question not addressed in our study is whether RUNX3 P1 methylation, as a surrogate of leukocyte influx, might classify gastric tumors into useful prognostic categories?" (PMID 26682246, 2015).
neuroblastoma (9 papers, 2014 to 2024). Neuroblastoma (NB) is the most common solid, extracranial childhood tumor. "Consistently, loss of RUNX3 was associated with an increase in TrkB signaling, which marks an unfavorable prognosis in patients with neuroblastoma." (PMID 36831211, 2023). "The epigenetic inactivation of RUNX3 expression, concomitant with the chromosome loss of 1p36 in neuroblastomas, is mediated at least in part by the enhancer of zeste 2 (EZH2)." (PMID 36831211, 2023). "Moreover, the RUNX3 deficiency attributed to deletion of the 1p36 region leads to worse prognosis in patients with neuroblastoma via TrkB." (PMID 36831211, 2023). "One mechanistic function of RUNX3 in neuroblastoma is its facilitation of the proteasomal degradation of MYCN, whereas several other underlying mechanisms have been suggested for its tumor suppressor activity in other type of cancers." (PMID 36831211, 2023). "Consistently, several patients categorized in the high-MYCN mRNA expression group who survived neuroblastoma concomitantly possessed high mRNA expressions of RUNX3, suggesting that RUNX3 has an ability to overcome the aggressive behavior of MYCN." (PMID 36831211, 2023). "A chromosomal deletion of the major tumor-suppressor center 1p36-35, in which RUNX3 is epigenetically inactivated, is frequently present in diverse cancer types, including 20% to 40% of cases of patients with neuroblastoma." (PMID 36831211, 2023). "Collectively, deficiency of both RUNX3 and p73 caused by deletion of the 1p36 region is likely to provide a favorable environment for MYCN-driven neuroblastomas." (PMID 36831211, 2023). "In human neuroblastoma cells RUNX3 gene transcriptional activity has been shown to be under negative control by EZH2, the histone methyltransferase catalytic subunit of the polycomb repressive complex 2 (PRC2)." (PMID 34360553, 2021). "RUNX3 was also highly expressed in osteosarcoma when compared with normal tissue, neuroblastoma, Wilm’s tumor, hepatoblastoma, retinoblastoma, and rhabdomyosarcoma." (PMID 33924679, 2021). "However, in primary neuroblastomas, RUNX3 acts as a tumor-suppressor, whereas RUNX1 bifunctionally regulates cell proliferation according to the characterized genetic and epigenetic backgrounds, including MYCN oncogenesis." (PMID 36831211, 2023). "Considering EZH2 as a potential epigenetic repressor of RUNX3, there could be a regulatory mechanism for the MYCN protein by mutually exclusive binding to oncogenic EZH2 or tumor-suppressive RUNX3 in neuroblastomas." (PMID 36831211, 2023). "Accordingly, decreased expression of RUNX3 mRNA is significantly correlated with a partial deletion at chromosome 1p36 as well as poor survival rate, arguing for a tumor suppressor role for RUNX3 in neuroblastoma." (PMID 36831211, 2023). "Overexpression of RUNX3, a member of the Runt family of transcription factors, has been shown to downregulate TrkB while promoting TrKC expression in developing dorsal root ganglia and in differentiated neuroblastoma cells." (PMID 34360553, 2021). "Indeed, we have recently found that the tumor suppressor protein Runx3 directly binds to MYCN in neuroblastoma cells and promotes degradation of MYCN in the ubiquitin–proteasome system dependent manner." (PMID 24391509, 2014).